CRBN (cereblon)
Diseases named in the same sentence as CRBN in open-access papers (continued):
Sharing a sentence is not in itself a finding about the gene and the disease.
colorectal cancer (3 papers, 2021 to 2025). A primary or metastatic malignant neoplasm that affects the colon or rectum. "Using this workflow, we report frequently dysregulatedproteins in colorectal cancer cells and uncover cell-dependent proteindegradation profiles of seven cereblon E3 ligase modulators (CRL4CRBN)." (PMID 35848491, 2022). "For example, IOX1-PROTAC, CRBN-recruiting PROTAC molecule synthesized using IOX1, effectively degraded KDM3 family and suppressed the self-renewal ability of colorectal cancer stem cells by disrupting Wnt/β-catenin signaling." (PMID 39938867, 2025). "MZ1 degrades BRD4 in colorectal cancer cell lines resistant to the BET degrader dBETi, which hijacks cereblon and not VHL." (PMID 36046113, 2021).
COVID-19 (3 papers, 2021 to 2025). A disease caused by infection with severe acute respiratory syndrome coronavirus 2. "One example is the expansion of platelets in severe COVID-19 samples, comprising CRBN/RBX1-high (M33) and IFITM3-high (M34) subpopulations." (PMID 41066207, 2025). "From the PBMCs of influenza- and COVID-19–infected patients, MSC identified 2 platelet subpopulations expanded in patients with severe COVID-19—namely, CRBN/RBX1-high (M33) and IFITM3-high (M34) cells." (PMID 41066207, 2025). "One example is the expansion of platelets in severe COVID-19 samples, comprised of CRBN/RBX1-high (M33) and IFITM3-high (M34) subpopulations." (PMID 39764102, 2024). "From the PBMC of influenza and COVID-19 infected patients, MSC identified two platelet subpopulations expanded in severe COVID-19 patients, namely, CRBN/RBX1-high (M33) and IFITM3-high (M34) cells." (PMID 39764102, 2024).
diffuse large B-cell lymphoma (3 papers, 2017 to 2024). "CC-122 is a pleiotropic pathway modifier that also binds CRBN and promotes degradation of Aiolos and Ikaros in diffuse large B-cell lymphoma (DLBCL) T-cells in in vitro and in vivo models and in patients, resulting in both cell autonomous and immune-stimulatory effects." (PMID 28298557, 2017). "In comparison, previously discovered CRBN-based heterobifunctional BCL6 degraders did not achieve complete BCL6 degradation and failed to induce a significant phenotypic response in diffuse large B-cell lymphoma (DLBCL)." (PMID 38607017, 2024).
gastric cancer (3 papers, 2021). A primary or metastatic malignant neoplasm involving the stomach. "The effect of ARV-825 in gastric cancer cells is associated with CRBN expression." (PMID 34733788, 2021). "By contrast, overexpression of CRBN in gastric cancer cells significantly increased the sensitivity of AGS and SGC7901 cells to ARV-825." (PMID 34733788, 2021). "For example, colorectal and gastric cancers have relatively high CRBN expression and activity, signifying their potential as top cancer indications to consider when developing CRBN-mediated protein degradation strategies." (PMID 34215850, 2021). "Only stomach cancer exhibited CRBN mRNA upregulation compared to normal stomach tissues." (PMID 33916291, 2021). "Our results revealed that CRBN expression had a major part to play in the inhibition of ARV-825 in gastric cancer cells; knockdown CRBN could decrease the inhibition of ARV-825 in MGC803 and HGC27 cells." (PMID 34733788, 2021). "Knockdown or overexpression CRBN could increase or decrease, respectively, the ARV-825 IC50 of gastric cancer cells." (PMID 34733788, 2021).
ischemia (3 papers, 2018 to 2021). A hypoperfusion of the BLOOD through an organ or tissue caused by a PATHOLOGIC CONSTRICTION or obstruction of its BLOOD VESSELS, or an absence of BLOOD CIRCULATION. "CRBN KO mice attenuated myocardial ischemia-reperfusion injury as well as ameliorated alcoholic liver disease." (PMID 33658395, 2021). "We have identified a decrease in the levels of CRBN following ND-13 treatment (ND-13: 1.77E+07 ±3.55E+06; Vehicle: 1.19E+08 ±2.52E+07; fold change: 6.7, p<0.01), suggesting an increase in the surface expression of functional KB channels that, in turn, improve the survival of cells after ischemia." (PMID 29489843, 2018). "CRBN also suppressed deleterious α-T172 phosphorylation in a rat model of cerebral ischemia (middle cerebral artery occlusion/reperfusion) in response to thalidomide, a known CRBN modulator, and attenuated cardioprotective AMPK activation in mouse hearts in response to ischemia/reperfusion." (PMID 33513781, 2021).
Obesity (3 papers, 2017 to 2021). Accumulation of substantial excess body fat. "For example, the loss of the CRBN gene protected mice from obesity, fatty liver, and insulin resistance induced by a high-fat diet." (PMID 33658395, 2021). "Many diseases, such as cardiovascular disease, obesity, and fatty liver, have been linked to the CRBN-mediated inactivation of AMPK." (PMID 28894755, 2017). "CRBN-deficient mice showed the activation of AMPK and resistance to high-fat diet-induced obesity and insulin resistance." (PMID 29410497, 2018). "Many animal experiments have shown that the inhibition of CRBN reduces the genesis of cardiovascular disease and obesity: could this be the same in humans?" (PMID 28894755, 2017).
Thrombocytopenia (3 papers, 2022 to 2025). A reduction in the number of circulating thrombocytes. "XZ739 was developed to overcome thrombocytopenia due to reduced CRBN E3 ligase expression in platelets." (PMID 40704654, 2025). "Moreover, it has been shown that PROTAC is a good strategy for combating on-target toxicity, such as thrombocytopenia caused by Bcl-xL inhibition, by taking advantage of the differential context expression of E3 ligase, von Hippel-Lindau (VHL) and celeblon (CRBN) 34-36." (PMID 36438482, 2022).
autosomal recessive non-syndromic intellectual disability (2 papers, 2017 to 2024). Autosomal recessive form of non-syndromic intellectual disability. "Specifically, disrupting mutations in CRBN, the gene that encodes cereblon/CRBN, an E3 ubiquitin ligase complex component, cause a form of autosomal recessive non-syndromic intellectual disability (ARNSID) that heavily impairs learning and memory skills." (PMID 38514794, 2024). "Destabilizing mutations in the human CRBN gene cause a form of autosomal recessive non-syndromic intellectual disability (ARNSID) that is modelled by knocking-out the mouse Crbn gene." (PMID 38514794, 2024).
Cerebral ischemia (2 papers, 2018 to 2021). Restriction of arterial blood supply to the brain associated with insufficient oxygenation to support the metabolic requirements of the tissue. "However, when thalidomide is administered to cerebral ischemia models, thalidomide binds to CRBN and the AMPK–CRBN interaction might be stabilized." (PMID 29410497, 2018).
diabetes (2 papers, 2022 to 2023). "Using insulin mutagenesis of neonatal diabetes variant-C43G and maturity-onset diabetes of the young 10 (MODY10) variant-R46Q, UDP-glucose:glycoprotein glucosyltransferase 1 (UGGT1) protects cereblon-dependent proinsulin ubiquitination in the ER." (PMID 36028536, 2022). "The expression of the hepatic cereblon (CRBN) and b-cell translocation gene 2 (BTG2) genes was significantly increased in fasting mice, diabetic mice, and patients with diabetes." (PMID 37488285, 2023). "Taken together, these findings suggest that the hepatic CRBN, CREBH, and BTG2 genes are upregulated during fasting and in patients with diabetes." (PMID 37488285, 2023).
lung adenocarcinoma (2 papers, 2021 to 2025). A carcinoma that arises from the lung and is characterized by the presence of malignant glandular epithelial cells. "Survival analysis demonstrated that overall survival was significantly positively correlated with CRBN expression in some cancer types including lung adenocarcinoma (LUAD), kidney renal clear cell carcinoma (KIRC), and skin cutaneous melanoma (SKCM)." (PMID 33916291, 2021). "CRBN expression was found to be significantly reduced in cancer tissues compared to normal tissues and was positively correlated with patient survival in multiple types of cancers including kidney renal clear cell carcinoma, lung adenocarcinoma, and skin cutaneous melanoma." (PMID 33916291, 2021). "The role of CRBN in enhancing MGD sensitivity was further validated through CRBN overexpression and NEC-driving factor expression experiments in non-NEC and lung adenocarcinoma cells." (PMID 40551250, 2025). "CRBN overexpression in non-NEC cells significantly increased their sensitivity to GSPT1 MGDs, as did the ectopic expression of NEC-driving factors, which upregulated CRBN levels in lung adenocarcinoma cells." (PMID 40551250, 2025).
memory impairment (2 papers, 2018 to 2024). "Taken together, these data show that knocking-out Crbn in mice, while preserving most behavioural traits, causes a remarkable memory impairment, and underline the necessity for CRBN molecules selectively located on telencephalic excitatory neurons for a proper cognitive function." (PMID 38514794, 2024). "Moreover, a BK channel opener can significantly improve the learning and memory impairment in CRBN mutant mice." (PMID 29370161, 2018). "Behavioural testing revealed a profound memory impairment in CRBN-KO and Glu-CRBN-KO but not GABA-CRBN-KO mice." (PMID 38514794, 2024).
ovarian carcinoma (2 papers, 2021 to 2023). A malignant neoplasm originating from the surface ovarian epithelium. "Genomic analysis of the ovarian-carcinoma A1847 cells resistant to CRBN- or VHL-recruiting PROTACs, revealed the amplification of the ABCB1 gene associated with increased expression of mRNA and protein." (PMID 36986673, 2023). "The first evidence of the resistance to PROTACs was demonstrated in vitro in ovarian-cancer cells exposed to CRBN- and VHL-recruiting PROTACs targeting BET proteins." (PMID 36986673, 2023). "Moreover, CRBN protein expression in ovarian cancer was not significantly altered, unlike mRNA expression." (PMID 33916291, 2021).
primary effusion lymphoma (2 papers, 2021 to 2022). A large B-cell lymphoma located in the body cavities, characterized by pleural, peritoneal, and pericardial fluid lymphomatous effusions and that is always associated with human herpes virus-8 (HHV-8). "Pom also induces direct cytotoxicity in primary effusion lymphoma (PEL), a B-cell malignancy caused by KSHV, in part through downregulation of IRF4, cMyc, and CK1α as a result of its interaction with cereblon, a cellular E3 ubiquitin ligase." (PMID 33411730, 2021).
systemic lupus erythematosus (2 papers, 2021 to 2022). An autoimmune multi-organ disease typically associated with vasculopathy and autoantibody production. "iberdomide is a novel compound with higher affinity for CRBN and the lowest IC50 of all thalidomide analogues, and is currently under clinical development for the treatment of systemic lupus erythematosus (SLE) and relapsed/refractory multiple myeloma (RRMM)." (PMID 35640596, 2022).
acute leukemia (1 paper, 2025). A clonal (malignant) hematopoietic disorder with an acute onset, affecting the bone marrow and the peripheral blood. "MA203 accelerates CRBN‐dependent proteasomal degradation of CHK1 in solid tumor‐derived cells and acute leukemia cells." (PMID 41104666, 2025).
acute lymphoblastic leukemia (1 paper, 2022). Leukemia with an acute onset, characterized by the presence of lymphoblasts in the bone marrow and the peripheral blood. "Since CRBN is poorly expressed in platelets, they designed another PROTAC XZ739 containing CRBN ligand and ABT263, treating T cell acute lymphoblastic leukemia (T-ALL) with less toxicity to platelets." (PMID 35410300, 2022).
Anxiety (1 paper, 2024). Intense feelings of nervousness, tension, or panic often arise in response to interpersonal stresses. "Cereblon has been speculated to be involved in regulating anxiety-like behaviors, and since anxiety and substance use co-occur frequently, the role of cereblon in inducing anxiety prompted substance use needs further investigation." (PMID 38660223, 2024).
atherosclerosis (1 paper, 2026). A disease characterized by the build-up of fatty material and calcium deposition in the arterial wall resulting in partial or complete occlusion of the arterial lumen. "Our findings provide the evidence that CRBN is a viable therapeutic target in atherosclerosis." (PMID 41424849, 2026). "In this study, we confirm that in an atherosclerosis model, endothelial KSR2 competes with CRBN to bind the N-terminal of AMPKα1, particularly at the K52 site." (PMID 41424849, 2026). "Our data further demonstrate that, in response to atherosclerosis-related stimuli, CUL4A, DDB1, and CRBN undergo marked cytoplasmic translocation in endothelial cells, leading to increased formation of cytoplasmic CRL4ACRBN complexes." (PMID 41424849, 2026).
autism (1 paper, 2021). Persistent deficits in social interaction and communication and interaction as well as a markedly restricted repertoire of activity and interest as well as repetitive patterns of behavior. "Fetuses exposed to thalidomide in early pregnancy were at risk of neurodevelopmental disorders such as autism, suggesting that CRBN is involved in prenatal brain development." (PMID 33777938, 2021).
autism spectrum disorder (1 paper, 2024). A spectrum of developmental disorders that includes autism, and Asperger syndrome. "As a previous study had linked alterations in CRBN copy number to autism spectrum disorders, we evaluated sociability and depressive-like behaviours, two core symptoms of those disorders." (PMID 38514794, 2024).
brain tumors (1 paper, 2024). "Therefore, thalidomide derivatives/immunomodulatory drugs with <450 molecular weight, which bind to CRBN and lead to degradation of GSPT1, are potentially effective therapeutics for primary brain tumors." (PMID 39117611, 2024).
cerebral infarction (1 paper, 2018). An ischemic condition of the brain, producing a persistent focal neurological deficit in the area of distribution of the cerebral arteries. "It has a possibility that CRBN directly regulates insulin-dependent signaling pathway in the molecular mechanism of thalidomide’s neuroprotective effect on cerebral infarction." (PMID 29410497, 2018). "Here we examined the molecular mechanism of thalidomide’s neuroprotective effect on cerebral infarction, focusing on its target protein, CRBN, and its binding protein, AMPK." (PMID 29410497, 2018).
channelopathy (1 paper, 2022). Channelopathies are a group of diseases caused by the dysfunction of ion channel subunits or their interacting proteins.
cholangiocarcinoma (1 paper, 2021). A carcinoma that arises from the intrahepatic biliary tree (intrahepatic cholangiocarcinoma) or from the junction, or adjacent to the junction, of the right and left hepatic ducts (hilar cholangiocarcinoma). "Nonetheless, two types of cancer exhibited CRBN upregulation, namely cholangiocarcinoma (CHOL) and liver hepatocellular carcinoma (LIHC)." (PMID 33916291, 2021).
chronic obstructive pulmonary disease (1 paper, 2022). A chronic and progressive lung disorder characterized by the loss of elasticity of the bronchial tree and the air sacs, destruction of the air sacs wall, thickening of the bronchial wall, and mucous accumulation in the bronchial tree. "However, little is known about the roles of CRBN in chronic obstructive pulmonary disease (COPD) pathogenesis." (PMID 36290703, 2022).
Cognitive impairment (1 paper, 2018). Abnormal cognition is characterized by deficits in thinking, reasoning, or remembering. "Recently, the mechanism of cognitive impairment due to a loss-of-function mutation in CRBN, a molecular target of thalidomide, has been elucidated." (PMID 30518785, 2018).
DeSanto-Shinawi syndrome (1 paper, 2021). "All disorders related to these genes include ADHD among their clinical manifestations: KIF11 is responsible for a disorder with microcephaly and lymphedema (OMIM #152950), WAC for Desanto-Shinawi syndrome (#616708), and CRBN is responsible for a recessive intellectual disability syndrome (#616708)." (PMID 35052433, 2021).
ductal carcinomas (1 paper, 2007). "Majority of genes encoding proteins with enzyme activity or implicated in metabolism were also upregulated in ductal carcinomas (STK4, SLC1A2, B3GALT3, OSBPL10, CRBN, CHML, YWHAB)." (PMID 17389037, 2007).
emphysema (1 paper, 2022). "The objective of this study was to investigate the role of CRBN in the development of elastase-induced emphysema in mice and the associated molecular mechanisms." (PMID 36290703, 2022). "To investigate the functional role of CRBN in emphysema development in the human lung, we first measured CRBN expression in surgically resected human lung tissues with immunoblotting." (PMID 36290703, 2022). "This study provides new evidence for the therapeutic potential of targeting CRBN for the treatment of COPD/emphysema." (PMID 36290703, 2022). "Our present findings show that decreased CRBN contributes to the development of emphysema by increasing neutrophilic inflammation, oxidative damage, and proteinase (MMP9) expression." (PMID 36290703, 2022). "To investigate the role of CRBN in modulating elastase-induced emphysema, we used Crbn knockout (KO) mice." (PMID 36290703, 2022). "However, whether CRBN affects lung emphysema, and the underlying mechanisms of emphysema pathogenesis are not known." (PMID 36290703, 2022).
heart failure (1 paper, 2026). Inability of the heart to pump blood at an adequate rate to meet tissue metabolic requirements. "Similarly, in heart failure models with reduced ejection fraction, CRBN impairs cardiac contractility by targeting Cav1.2α for CRL4ACRBN -mediated degradation, whereas TD-165 treatment improved cardiac function in both in vitro and ex vivo settings." (PMID 41424849, 2026).
idiopathic pulmonary fibrosis (1 paper, 2021). Idiopathic pulmonary fibrosis (IPF) is a nonneoplastic pulmonary disease that is characterized by the formation of scar tissue within the lungs in the absence of any known cause. "Interventions that target a regulatory protein called cereblon could help reduce the damage inflicted on the lungs by idiopathic pulmonary fibrosis (IPF)." (PMID 34002012, 2021).
injury (1 paper, 2024). Damage inflicted on the body as the direct or indirect result of an external force, with or without disruption of structural continuity. "The preservation of these antioxidants in the CRBN-KO cells further supports the role of CRBN in oxidative stress, which is a key player in the pathogenesis of liver injury." (PMID 39139558, 2024).
lentivirus infection (1 paper, 2025). Virus diseases caused by the Lentivirus genus. "Western blotting analysis was used to detect LMO2, endogenous CRBN, and VH576-L10-CRBN levels after lentivirus infection." (PMID 41385269, 2025).
liver diseases (1 paper, 2024). "Overall, these results suggest the crucial role of CRBN in mediating the hepatocellular response to oxidative stress and inflammation triggered by CCl4 exposure, offering potential clinical implications for liver injury in a wide range of liver diseases." (PMID 39139558, 2024). "In conclusion, the present study not only highlights the protective role of CRBN deletion against CCl4-induced hepatocellular injury, but also provides a foundation for further investigations into gene-targeted therapies for liver injury across a spectrum of liver diseases." (PMID 39139558, 2024).